TGFB3 (transforming growth factor beta 3)
Diseases named in the same sentence as TGFB3 in open-access papers (continued):
Sharing a sentence is not in itself a finding about the gene and the disease.
cancer (98 papers, 2003 to 2025). A tumor composed of atypical neoplastic, often pleomorphic cells that invade other tissues. "The results indicated that TGFβ3 is associated significantly with different cancer types and participates in many cancer signaling pathways, including hippo and proteoglycan signaling and pluripotent stem cell regulations." (PMID 40027190, 2025). "Our study found multiple genes in the cancer pathway that are associates with the progression or suppression of cancer such as laminin, Tgfβ3, Hhip, Arnt2 and Mmp2." (PMID 32330152, 2020). "Repositioning of either SP100 or TGFB3 towards the nuclear periphery was associated with low Gleason score whereas repositioning towards the interior was a marker of higher Gleason score cancers." (PMID 31681438, 2019). "A more peripheral position of SP100 and TGFB3 in the nucleus, compared to benign tissues, is associated with low Gleason score cancers, whereas more internal positioning correlates with higher Gleason scores." (PMID 31681438, 2019). "A very strong adverse effect on RFS (p = 0.0001) was seen with TGFB3, in line with the central role of the associated signaling pathways in cancer, and with PTGER3 (p <0.0001), encoding a prostaglandin E2 receptor." (PMID 27215396, 2016). "Glycoprotein-A repetitions predominant (GARP) is a cell surface docking receptor for activating latent TGFβ1, TGFβ2, and TGFβ3, with its expression restricted predominantly to effector Treg and cancer cells." (PMID 38085441, 2024). "All three genes were involved in KEGG pathway hsa05166: Human T-cell leukemia virus 1 infection pathway and both ETS1 and TGFB3 were in KEGG pathway hsa05200: Pathways in cancer." (PMID 37848499, 2023). "The research of key cis-lncRNA SLC12A5-AS1, AC243829.4 and TGFB3 mainly concentrated in cancer and immune respone." (PMID 37369992, 2023). "We found that Tgfb3 colocalized with Dusp1 which is known as a crucial participator in multiple diseases and cancers." (PMID 36820224, 2023). "Consistent with the cancer hallmark analysis, TNF (TNFSF13B), TGFB1, and TGFB3 played important roles in the mesenchymal microenvironment crosstalk." (PMID 37370765, 2023). "In detail, activated transcription factors, such as FOXO1, HIF1A, STAT3, and JUN, regulate the expression of TGFB1, TGFB3, IL1B, and TNF, promoting cancer hallmarks associated with these ligands." (PMID 37370765, 2023). "While extensive research has been conducted on the role of TGFβ1 in other wasting conditions such as muscle dystrophy, the contribution of TGFβ2 and TGFβ3 to cancer cachexia remains unexplored." (PMID 37701438, 2023). "We found ENPEP is correlated with TGF‐β coding genes TGFB1(80%), TGFB2(64%), TGFB3(88%) in most cancers." (PMID 34862755, 2022). "TGFβ defines three subtypes (TGFβ1, TGFβ2, and TGFβ3), of which TGFβ is highly expressed in many cancers, especially those showing high dissemination potential." (PMID 36119489, 2022). "Our experiments confirmed the inhibitory effect of TGFβ3 on adipogenic differentiation and thereby provide a plausible link between the cancer cell secretome, MSC HA-matrix synthesis and MSC differentiation potential." (PMID 34707175, 2021). "Both SP100 and TGFB3 contributed to the increased proportion of cancer specimens with repositioning events." (PMID 31681438, 2019). "As with Gleason score, in the more highly differentiated cancers (Gleason grades 1-3) SP100 and TGFB3 repositioned towards the nuclear periphery in 100% (5 and 3 cancers, respectively) of the cancers in which these genes repositioned." (PMID 31681438, 2019). "Both SP100 and TGFB3 shifted to a more peripheral position in 100% of the low Gleason score cancers in which these genes showed an altered radial position." (PMID 31681438, 2019). "TGFB3 repositioned in 41.7% (5/12) of T1/2 cancers, 11.1% (1/9) of T3/4 cancers, and 7.7% (1/13) of benign tissues, compared to the PND." (PMID 31681438, 2019).
cancer (continued). "More peripheral positioning was detected in one high Gleason score specimen for both SP100 and TGFB3, resulting in a false positive rate of 6.3% (1/16) and 8.3% (1/12), respectively, for intermediate and high Gleason score cancers." (PMID 31681438, 2019). "In contrast, SP100 and TGFB3 were in a more internal position in 83.3% (5/6) and 75.0% (3/4), respectively, of the Gleason score 7 and higher cancers in which they repositioned." (PMID 31681438, 2019). "The remaining 28 ‘cancer’ genes identified as upregulated and hypomethylated, as with the acute RE analysis, this included those implicated in TGF-beta signalling (TGFB3, TGFBR2, LEF1 and MECOM) after chronic RE in human skeletal muscle." (PMID 30862794, 2019). "In keeping with previous studies, we find similar positioning patterns for both SP100 and TGFB3 amongst normal tissues and between normal and benign disease tissues, highlighting that the gene repositioning in cancer tissues were specific to cancer." (PMID 31681438, 2019). "Even though the positioning patterns of SP100 and TGFB3 are inferior to the Gleason system at stratifying cancers, our results reveal subtype-specific genome organization." (PMID 31681438, 2019). "SP100 was more internally positioned in 80% (4/5) of Gleason grade 4 and 5 cancer in which SP100 repositioned and TGFB3 was more internally positioned in 66.7% (2/3) of the Gleason grade 4 and 5 cancers in which TGFB3 was repositioned, compared to the PND." (PMID 31681438, 2019). "TGFB3 repositioned in 30% (3/10) low Gleason score cancer tissues, 20% (1/5) of intermediate Gleason score cancers, and 42.9% (3/7) of high Gleason score cancers." (PMID 31681438, 2019). "We therefore evaluated if combining positioning data from SP100 and TGFB3 would increase the number of cancers classified as low or intermediate/high Gleason score based on gene positioning patterns." (PMID 31681438, 2019). "With regard to the circulating levels of CD105, TGFβ1, TGFβ3 and the receptor–ligand complexes, the results indicate that except for TGFβ1, the levels of the other molecules were markedly elevated in cancer patients compared with controls." (PMID 12778073, 2003). "The same trend was noticed with CD105/TGFβ3, that is, a lower level in controls compared with cancer patients." (PMID 12778073, 2003). "It would be interesting to further investigate whether the synergy observed between TGFβ3 and palbociclib is observable in other cancer types in which palbociclib treatment is being studied." (PMID 38831405, 2024). "In addition, TGFβ1 and TGFβ3 were negatively associated with MATH, which is prevalent in most cancer patients and is a major driver of acquired resistance to cancer therapy." (PMID 36119489, 2022). "KEGG analysis showed that ACVR1, SMAD1, ZFYVE9, BMPR1B, and TGFB3 were related to regulating proteoglycan in cancer, focal adhesion, tight junction, PI3K-Akt signaling pathway, cell adhesion molecules (CAMs), Rap1 signaling pathway, osteoclast differentiation, and Hippo signaling pathway." (PMID 34725559, 2021). "Periostin expression in lung fibroblasts may be modulated by cancer cells through the secretion of transforming Growth Factor Beta 3 (TGFβ3)." (PMID 34201840, 2021). "However, the false positive rate for using a more peripheral positioning of TGFB3 was relatively low at 8%, because it was more peripherally positioned in two of the 25 benign tissues and higher Gleason score cancers." (PMID 31681438, 2019). "Similarly, TGFB3 was more internally positioned in three (3/7; 42.9%) cancers and more peripherally positioned in four (57.1%)." (PMID 31681438, 2019).
cancer (continued). "Importantly for multiplexing to improve the sensitivity, SP100 and TGFB3 would need to be frequently repositioned in different cancer specimens." (PMID 31681438, 2019). "Notably, this included TGF-β (TGFB1, TGFB3), drivers of adenosine-mediated immune suppression (NT5E (CD73), ENTPD1 (CD39)), Wnt pathway ligands (WNT7A, WNT4), IL10 and drivers/markers of cancer-associated fibroblast activation (INHBA, WNT7A, TGFB1, FAP, PDGFRA, PDGFRB)." (PMID 39568014, 2024). "Currently, most cancer and fibrotic EMT are regulated by TGFβ1, while TGFβ2 primarily controls EndMT in the heart development, and TGFβ3 mediates EMT in development." (PMID 36882799, 2023). "Not only that, in the two cancers, the most significant correlation difference was the TGF-β gene (TGFB1, TGFB3)." (PMID 36207751, 2022). "The expression levels of TGFB2 and TGFB3 were extremely low, while the TGFB1 expressed dominantly in the monocytes in blood and the macrophages in cancer tissues." (PMID 35069521, 2021). "Despite the fact that low Gleason score cancers represents fairly well differentiated tissues there were distinct positioning patterns for SP100 and TGFB3 between low Gleason score cancers and benign disease, which are considered differentiated tissues." (PMID 31681438, 2019). "Based on RNA-seq data from the cancer cell line encyclopedia, HepG2 cells expressed much higher levels of TGFB1 than TGFB2 or TGFB3." (PMID 31462641, 2019). "Of a subset of 19 cancer tissues in which both genes were positioned, 10 (52.6%) had differential repositioning patterns for SP100 to that of TGFB3." (PMID 31681438, 2019). "TGFB3 and LMNA were both more frequently repositioned in low T stage cancers to that of high T stage cancers, but with high false positive rates." (PMID 31681438, 2019). "Enriched genes also included factors involved in cancer pathways and PI3K/AKT signalling, including IRS1, BCL2, TGFB3 and FGF18." (PMID 26698305, 2015). "TGFB3, GINS3 and BAG1 have also been reported to be involved in cancer cell proliferation and invasion." (PMID 23977152, 2013). "Notably, TGFβ3 is a less researched member of the TGFβ family, and emerging evidence indicates TGFβ3 signaling promotes EMT and cell mobility in cancer cells." (PMID 40027190, 2025). "SP100, TGFB3 and MMP9 each map to different chromosomes (HSA 2, 14 and 20, respectively) and therefore represent independent repositioning events within the subgroups of different Gleason score cancers." (PMID 31681438, 2019). "Unlike SP100, the direction TGFB3 reposition in the normal tissue was the same as in low Gleason score cancer." (PMID 31681438, 2019). "Constant with this, we find that multiplexing SP100 and TGFB3 reduces the false negative rate of detecting intermediate and higher Gleason score cancers." (PMID 31681438, 2019). "For one cancer sample, both genes were repositioned, compared to their PND, but they relocated in opposite directions, with SP100 being more peripherally positioned, while TGFB3 was more internally positioned." (PMID 31681438, 2019). "For six of these cancers SP100 was repositioned but TGFB3 was not, whereas in three cancers only TGFB3 was repositioned." (PMID 31681438, 2019). "As in other cancers, we observed high expression of TGFB1 and TGFB3 in Group 3 MB." (PMID 31328883, 2019). "Interestingly, TGFb3 is a known inducer of both periostin and NEDD9, both of which have been reported as frequently overexpressed in a variety of human cancers." (PMID 23372733, 2013). "In the present study MATH was lower when TGFβ1 and TGFβ3 were higher, while higher levels of TGFβ promoted the formation of an immunosuppressive microenvironment and facilitated the progression of EMT, conditions that favored the evolutionary development of cancer cells." (PMID 36119489, 2022). "However, multiplexing with a more peripheral position of either SP100 or TGFB3 did not reduce the false negative rate for low Gleason score cancers from that of using SP100 alone." (PMID 31681438, 2019).
cancer (continued). "The positioning patterns of SP100 and TGFB3 could not distinguish intermediate Gleason score cancer tissues from high Gleason score cancer tissues." (PMID 31681438, 2019). "Thus, in addition to the high false negative rate for Gleason score, SP100 and TGFB3 can not distinguish aggressive low Gleason score cancers from non-aggressive low Gleason score cancers, limiting their clinical potential." (PMID 31681438, 2019). "Likewise, TGFB3 repositioned in 33.3% (1/3) of metastatic low Gleason score cancer specimens and 28.8% (2/7) of non-metastatic low Gleason score cancer specimens." (PMID 31681438, 2019). "However, SP100 and TGFB3 were repositioned in a similar proportion of low Gleason score cancers with or without metastasis." (PMID 31681438, 2019). "The repositioning patterns of SP100 and TGFB3 could not distinguish intermediate from high Gleason score cancers." (PMID 31681438, 2019). "We find TGFB1 and TGFB3 gene are shown in normal HK genes group, which do not express in cancer." (PMID 23382867, 2013). "These genes have various implications for cancer therapy, and the detailed mechanism of action of DLG3, TGFB3, TGFBR1 and FZD6 genes in GC has not been studied, and needs further researches to explore." (PMID 36712672, 2022). "Using a more internal positioning pattern as a biomarker of intermediate and high Gleason score cancers resulted in a false negative rate of 62.5% (10/16) and 66.7% (8/12) for SP100 and TGFB3, respectively." (PMID 31681438, 2019). "We also noted high baseline expression of several other potential therapeutic targets including VEGFB, TGFB3, PDGFB/PDGFRB, FGFR1 and IGF1R in cancers that did not achieve pCR." (PMID 30967156, 2019). "Consistent with Gleason score, the direction that SATB1 and LMNA repositioned did not aid in stratifying cancers by Gleason grade, but the direction of repositioning did correlate with Gleason grade for SP100 and TGFB3." (PMID 31681438, 2019). "The proportion of cancers in which SP100 and TGFB3 repositioned also did not stratify Gleason score groups." (PMID 31681438, 2019).
infection (14 papers, 2008 to 2025). The state of being infected such as from the introduction of a foreign agent such as serum, vaccine, antigenic substance or organism. "Infection increased brain expression of both Tgfb1 and Tgfb3 mRNAs beginning at 3 days and a maximal 5–7 days after infection." (PMID 36016413, 2022). "To determine if these changes were unique to NSV, we also measured CNS levels of active TGFb1 and TGFb3 after infection with moderately virulent TE12 and relatively avirulent TE recombinant strains of SINV." (PMID 36016413, 2022). "The mRNA expressions of TLR3, TGFβ3 and SMAD7 in the lungs following infection with Pigeon04 were negatively correlated with viral replication." (PMID 21826229, 2011). "Even though we are focusing on the early response (8, 24 and 48 hpi) during the infection, the genes expressed differentially at day 21, include CCL5, CCR5, TGFB3 and AIF1, and provide additional gene profiling data during the chronic infection stage." (PMID 18811943, 2008). "Pro-inflammatory (IFNγ, IL-6, TNFα), Treg (IL-10, TGFβ1, TGFβ3), Th9 (IL-9), Th17 (IL-17), and Th2 (IL-4, IL-13) cytokines, total IgM and IgG, as well as gene expressions of FoxP3, STAT5+, IFNγ-R1, and ROR alpha+, were measured at day 1, day 7, day 14, day 21, and day 28 post-infection." (PMID 37569646, 2023).
cardiovascular disease (5 papers, 2015 to 2022). "In contrast, the role of TGFB3 in cardiovascular disease is very clear." (PMID 35845066, 2022). "Recently, Tgfb3 conditional knockout mice have been generated and will be useful in future investigation to determine the cell-specific role of TGFβ3 in cardiovascular development and adult cardiovascular disease." (PMID 32456345, 2020). "The relatively young age of previously reported patients with TGFB3 mutations (8 and 10.5 years of age) might explain the lack of obvious cardiovascular disease." (PMID 25835445, 2015). "Although cardiovascular disease was not the focus of the two studies, none of the studies reported any congenital heart defects in the Tgfb3−/− fetuses." (PMID 32456345, 2020).
connective tissue disorder (4 papers, 2020 to 2023). A disease involving the connective tissue. "In a second patient, with a suspicious family history, a genetic panel for connective tissue disorders identified a pathogenetic variant in TGFB3 gene." (PMID 37679850, 2023). "Since the family history was suspicious for connective tissue disorders, a genetic panel was performed and identified a pathogenetic variant in TGFB3 gene." (PMID 35668506, 2022). "Loeys-Dietz syndrome is a rare connective tissue disorder related to a pathogenic variant in TGFBR1, TGFBR2, SMAD2, SMAD3, TGFB2 or TGFB3 genes." (PMID 37679850, 2023).
inflammatory myopathies (4 papers, 2013 to 2025). "TGFB1 and TGFB3 were expressed at levels similar to other inflammatory myopathies, while their receptors—particularly those for TGFB2 and TGFB3—were more strongly upregulated in ANCA-negative VM than in other IIM subtypes." (PMID 41441888, 2025). "Thus, a deficiency of TGFB3 during early myogenesis could result in hypomyoplasia throughout development that clinically mimics, but is etiologically and histologically distinct from, the myopathy caused by excess TGF-β signaling found in MFS." (PMID 23824657, 2013). "Finally, TGFB1 and TGFB3 were upregulated in GM, with TGFB1 particularly overexpressed compared to other forms of myopathy." (PMID 40568658, 2025).
renal disease (3 papers, 2016 to 2022). "Estrogens or their associated metabolites can ameliorate the renal damage associated with lack of TGFβ3 function, as occurs in other renal diseases." (PMID 34431499, 2021).
cardiac disease (1 paper, 2020). "This raises a possibility whether TGFβ3 could represent the predominant TGFβ isoform during later stages of cardiac remodeling, a suggestion consistent with the mutations in TGFB3 in adult cardiac disease patients." (PMID 32456345, 2020).
skeletal diseases (1 paper, 2023). "For example, Transforming growth factor beta 2 (Tgfb2) and Tgfb3 are both linked to skeletal diseases." (PMID 37378024, 2023).
TGFB3 also shares sentences with these, for which no sentence is quoted: lupus (6 papers); diabetes (5); myopia (5); breast (4); oral mucositis (4); uterine fibroids (4); Arrhythmogenic right ventricular dysplasia (3); astrocytomas (3); diabetic nephropathy (3); endometriosis (3); liver cirrhosis (3); varicocele (3); Aortic dissection (2); cardiac arrhythmia (2); cardiac failure (2); chronic periodontitis (2); cutaneous melanoma (2); dissection (2); exfoliation syndrome (2); head and neck cancer (2); immune disorders (2); lymphoma (2); migraine (2); Ovarian Tumors (2); periodontal disease (2); primary open angle glaucoma (2); pyometra (2); retinal detachment (2); ulcer (2); Uterine leiomyoma (2).
A further 117 diseases each share a sentence with TGFB3 in 2 papers or fewer.